EPS8 (EGFR pathway substrate 8, signaling adaptor)
Description:
Signaling adapter that controls various cellular protrusions by regulating actin cytoskeleton dynamics and architecture. Depending on its association with other signal transducers, can regulate different processes. Together with SOS1 and ABI1, forms a trimeric complex that participates in transduction of signals from Ras to Rac by activating the Rac-specific guanine nucleotide exchange factor (GEF) activity. Acts as a direct regulator of actin dynamics by binding actin filaments and has both barbed-end actin filament capping and actin bundling activities depending on the context. Displays barbed-end actin capping activity when associated with ABI1, thereby regulating actin-based motility process: capping activity is auto-inhibited and inhibition is relieved upon ABI1 interaction. Also shows actin bundling activity when associated with BAIAP2, enhancing BAIAP2-dependent membrane extensions and promoting filopodial protrusions. Involved in the regulation of processes such as axonal filopodia growth, stereocilia length, dendritic cell migration and cancer cell migration and invasion. Acts as a regulator of axonal filopodia formation in neurons: in the absence of neurotrophic factors, negatively regulates axonal filopodia formation via actin-capping activity. In contrast, it is phosphorylated in the presence of BDNF leading to inhibition of its actin-capping activity and stimulation of filopodia formation. Component of a complex with WHRN and MYO15A that localizes at stereocilia tips and is required for elongation of the stereocilia actin core. Indirectly involved in cell cycle progression; its degradation following ubiquitination being required during G2 phase to promote cell shape changes.
Synonyms: DFNB102
Tractability: Antibody: its Gene Ontology location is reachable by antibodies, with medium confidence; the Human Protein Atlas places it where antibodies can reach. PROTAC: UniProt records ubiquitination sites on it; ubiquitination databases record sites on it; its protein half-life has been measured.
Gene: Protein-coding gene on chromosome 12 (15,620,134 to 15,882,330, reverse strand). Ensembl gene ENSG00000151491.
Subcellular location: Cytoplasm, cell cortex; Cell projection, ruffle membrane; Cell projection, growth cone; Cell projection, stereocilium; Synapse, synaptosome
Subcellular location (Human Protein Atlas): Plasma membrane
Pathways (Reactome):
Sensory Perception: Sensory processing of sound by inner hair cells of the cochlea; Sensory processing of sound by outer hair cells of the cochlea
Gene Ontology:
Molecular function: protein binding; actin binding; small GTPase binding
Biological process: actin crosslink formation; actin filament bundle assembly; actin polymerization-dependent cell motility; barbed-end actin filament capping; dendritic cell migration; exit from mitosis; positive regulation of ruffle assembly; Rac protein signal transduction; regulation of actin filament length; regulation of cell shape; regulation of Rho protein signal transduction; Rho protein signal transduction; regulation of postsynaptic membrane neurotransmitter receptor levels
Cellular component: extracellular exosome; vesicle; cell cortex; plasma membrane; ruffle membrane; stereocilium; brush border; glutamatergic synapse; growth cone; NMDA selective glutamate receptor complex; postsynaptic density; stereocilium bundle; stereocilium tip; synapse
Genetic constraint (gnomAD): Loss-of-function variants: 20 observed, 65.61 expected, observed/expected ratio (o/e) 0.3, 90% interval 0.21 to 0.44. The upper end of that interval is the gene's LOEUF score, 0.44, which puts it in group 1 of 6, group 1 being the genes least tolerant of losing a copy. Missense variants: 671 observed, 722.74 expected, observed/expected ratio (o/e) 0.93, 90% interval 0.87 to 0.99. Synonymous variants: 241 observed, 250.63 expected, observed/expected ratio (o/e) 0.96, 90% interval 0.87 to 1.07.
Gene-disease validity (ClinGen):
ClinGen rates the evidence that EPS8 causes each of these diseases.
autosomal recessive nonsyndromic hearing loss 102 (autosomal recessive): Moderate. Any autosomal recessive nonsyndromic deafness in which the cause of the disease is a mutation in the EPS8 gene.
Homologues: Orthologues: chimpanzee EPS8 (99% identical), macaque EPS8 (95% identical), dog EPS8 (94% identical), rabbit EPS8 (93% identical), guinea pig EPS8 (91% identical), pig EPS8 (91% identical), rat Eps8 (90% identical), mouse Eps8 (89% identical), tropical clawed frog eps8 (65% identical), zebrafish eps8a (59% identical). Paralogues in human: EPS8L2 (40% identical), EPS8L1 (36% identical), EPS8L3 (23% identical).
Diseases named in the same sentence as EPS8 in open-access papers:
EPS8 is named in the same sentence as 58 diseases in open-access papers, as found by Europe PMC text mining. Sharing a sentence is not in itself a finding about the gene and the disease. The quoted sentences say what the papers report.
breast carcinoma (12 papers, 2010 to 2023). "Small molecule inhibitors targeting the EGFR/Eps8 complex in NSCLC and breast cancer models have shown promising results, supporting Eps8 as a potential therapeutic target in cancer." (PMID 37169593, 2023). "On the contrary, Eps8 has been reported to be up-regulated in most cancer patients, including pituitary gland cancer, breast cancer, ovarian cancer, and so on." (PMID 35771226, 2022). "EE02 selectively suppressed growth and induced apoptosis in EGFR-positive and Eps8-positive breast cancer and NSCLC cells." (PMID 31118055, 2019). "This study focused on the screening of small-molecule inhibitors that target the EGFR/Eps8 complex in breast cancer and non-small cell lung cancer (NSCLC)." (PMID 31118055, 2019). "We identified EE02 as an EGFR/Eps8 complex inhibitor that demonstrated promising antitumor effects in breast cancer and NSCLC." (PMID 31118055, 2019). "EPS8 was overexpressed in all six breast cancer and NSCLC cell lines (MDA-MB-468, H460, A549, H1975, MCF-7 and BT549), moderate expressed in normal cell lines (MCF-10A and BEAS-2B) and very low expressed in IM-9 cell line." (PMID 31118055, 2019). "JNK2 inhibited the expression of epidermal growth factor receptor pathway substrate 8 (EPS8), which controlled the actin-based motility and were involved in regulating Rac-mediated cell migration, to promote the migration of mammary tumor cells." (PMID 28915613, 2017). "Another study meanwhile has suggested that Eps8 regulates ERK activity which affects migration of breast cancer cells." (PMID 27138333, 2016). "Study showed that DSCAM-AS1 may act as a competing endogenous RNA of miR-137 and regulates EPS8 to promote cell reproduction and suppresses cell apoptosis in TR breast cancer." (PMID 33046983, 2020). "Similar with our findings, serval studies have demonstrated EPS8, DSG2, ITGB6 were aberrantly expressed in pancreatic cancer, breast cancer, pituitary tumor, and gastric cancer." (PMID 36237305, 2022). "In human breast cancer cell line MDA-MB-231, the expression of EPS8 and CLDN1 genes depends on SATB1, and SATB1 binding sites have been found at multiple sites near and within genes encoding CLDN1 and EPS8 (based on our unpublished ChIP-seq results)." (PMID 31830989, 2019). "MDA-MB-468 is a breast cancer cell line that expresses high levels of EGFR and Eps8." (PMID 31118055, 2019). "A previous study by our group demonstrated an elevated expression of EPS8 in patients with acute myeloid leukemia (AML), its overexpression was inversely correlated with overall survival of patients, and EPS8 protein as a vaccine reagent induced a CTL response in a murine breast carcinoma model." (PMID 25936538, 2015).
ovarian carcinoma (9 papers, 2012 to 2025). A malignant neoplasm originating from the surface ovarian epithelium. "EMT in ovarian cancer cells is dependent on RAC1 activation through the SOS1/EPS8/ABI1 complex, associated with increased MEK-ERK and SRC activation." (PMID 39354505, 2024). "In sum, ABI1 is essential to promote metastasis in ovarian cancer through SOS1/EPS8/ABI1 complex activation, linked to regulations of inflammatory signaling and cytoskeletal reorganization." (PMID 39354505, 2024). "Thus, relatively high expression of EPS8 is a risk factor for ovarian cancer, which is consistent with our research results." (PMID 34825509, 2021). "We found that the expression of BANF1, CDK2AP2, DDT, LRIG1, MRPL4, and S100A13 was upregulated in ovarian cancer samples, and the expression of EPS8, NUCB2, PAF1, PMP22, RABGAP1L, and USO1 was upregulated in normal samples." (PMID 41000388, 2025). "High expression of GJB2, S100A2, SPOCK2, TGM1or EPS8 indicated a poor OS of patients with ovarian cancer, whereas ovarian cancer patients with higher expression of ADAMDEC1, CHEK1, EGFL6, FAM181A, FOXA2, LYPD1, PART1 or XPR1 possessed better OS." (PMID 31794425, 2019). "Therefore, the metastatic potential of ovarian cancer is closely related to the integrity of the SOS1/EPS8/ABI1 complex." (PMID 34825509, 2021). "In addition, some scholars have found that the presence of the SOS1/EPS8/ABI1 complex correlated well to the continuous epithelial–mesenchymal transition (EMT) characteristics of ovarian cancer cells, and an intact complex is required for this procedure." (PMID 34825509, 2021). "Therefore, silenced or low expression of EPS8 can reduce the migration and metastatic colonizing ability of ovarian cancer cells." (PMID 34825509, 2021). "The specific involvement of EPS8/ABI1/SOS1 tri-complex in ovarian cancer metastasis suggests that this tri-complex-targeted drugs may have less effects on non-cancer tissues than on cancer tissues." (PMID 31488087, 2019). "Our previous study demonstrated that LPA could stimulate Rac activation, cytoskeleton reorganization, and ovarian cancer cell migration through a signaling pathway consisting of Ras-SOS1/EPS8/ABI1 tri-complex." (PMID 31488087, 2019). "Our finding of Abi1 overexpression during the development of invasive carcinomas is comparable to findings made in ovarian cancer, where coexpression of the trimeric Abi1/SOS1/Eps8-complex is a prerequisite for Rac-dependent ovarial cancer cell motility upon lysophosphatidic acid (LPA)-stimulation." (PMID 22808230, 2012). "Blocking interaction between ABI1 and EPS8 in vivo suppresses LPA-induced invasion and metastasis of ovarian cancer cells." (PMID 39354505, 2024). "We aimed to develop inhibitory short peptides that can prevent protein interactions of SOS1/EPS8/ABI1 tri-complex, a key component essential for ovarian cancer metastasis." (PMID 31488087, 2019). "With the aid of a well-established peritoneal seeding model, we demonstrated that the presence of SOS1/EPS8/ABI1 tri-complex correlated well to the metastatic potential of ovarian cancer cells, and an intact SOS1/EPS8/ABI1 tri-complex is required for Rac activation." (PMID 31488087, 2019).
pancreatic cancer (9 papers, 2017 to 2024). "Eps8 has been observed to be highly expressed in exosomes from pancreatic cancer cells with metastatic characteristics, metastasis‐derived, indicating that exosomal Eps8 holds promise as a biomarker for pancreatic cancer metastasis." (PMID 39113699, 2024). "Eps8 is significantly increased in pancreatic cancer, and its expression is positively correlated with the migration potential of tumor cells." (PMID 36741321, 2023). "EPS8 knockdown dramatically reduced the migration and invasion capacity of pancreatic cancer cells in the CAPAN-1 cell line and PANC-1 cell line in the transwell experiment (**P<0.01)." (PMID 36275722, 2022). "EPS8 increased polyubiquitination by downregulating ALDH7A1 protein expression in pancreatic cancer." (PMID 36237305, 2022). "Most importantly, our study validated the results using cell lines and clinical samples and identified EPS8 as a novel marker for pancreatic cancer." (PMID 36275722, 2022). "Cell assays showed that in CAPAN-1 and PANC-1 cell lines, EPS8 knockdown significantly reduced the viability, clonogenesis, migration and invasion of pancreatic cancer cells." (PMID 36275722, 2022). "The activity of pancreatic cancer cells was dramatically reduced following EPS8 knockdown in CAPAN-1 and PANC-1 cell lines (*P<0.05, **P<0.01)." (PMID 36275722, 2022). "It was found that compared with para-tumor tissue, the expression of EPS8 in pancreatic cancer was significantly up-regulated (*P<0.05)." (PMID 36275722, 2022). "Clinical PCR assay of EPS8 expression showed that EPS8 expression was significantly up-regulated in pancreatic cancer (*P<0.05)." (PMID 36275722, 2022). "Eps8 is upregulated in pancreatic cancer and correlates with migration ability and tumor progression." (PMID 34957301, 2021). "All these genes are upregulated in pancreatic cancer, and seven of them are significantly associated with unfavorable prognosis (MET, YAP1, PTPN14, EPS8, AHNAK, RALB, and AFAP1)." (PMID 34957301, 2021). "Previously, scholars found that EPS8 was usually overexpressed in advanced thyroid cancer, pancreatic cancer, oral squamous cell carcinoma, and pituitary tumors." (PMID 34825509, 2021). "Similarly, LDHA, EPS8, SLC20A1 and ARNTL2 expression are also related to metastasis or shorter survival in pancreatic cancer." (PMID 32310997, 2020).
deafness (7 papers, 2012 to 2025). An inherited or acquired condition characterized by the complete loss of the ability to hear from one or both ears. "Mutations in EPS8 have been identified as causes of deafness and autosomal recessive 102 (DFNB102) (MIM#615974)-related hearing impairment." (PMID 36635257, 2023). "The deafness gene Eps8 (mice:; human:) encodes an actin-binding protein with multiple functions in the control of actin dynamics." (PMID 35235570, 2022). "To conclude, we report for the first time the identification of one biallelic nonsense mutation in EPS8, in two children affected by profound congenital deafness." (PMID 24741995, 2014). "The other 6 variants were associated with recessive forms of deafness (TMPRSS3, GPSM2, BDP1, EPS8, EPS8L2, and PCDH15)." (PMID 33809266, 2021). "However, the rescue of deafness genes crucial for the initial growth of the hair cell stereociliary bundles such as Eps8, Clarin‐1 and Sans have shown limited success." (PMID 41015536, 2025). "Mutations or absence of the stereociliary protein EPS8 cause deafness in humans and mice, respectively." (PMID 36034774, 2022).
lung carcinoma (4 papers, 2013 to 2019). "However, our work shows that other mechanisms for activating Erk, including via oncogenic Ras mutations in lung cancer cells or via serum factors in osteosarcoma cells also lead to Eps8-dependent bleb-based migration." (PMID 26163656, 2015). "We have shown that ITSN-1s expression in lung cancer cells impairs Eps8 interaction with mSos1 and facilitates Eps8-Cbl interaction leading to ubiquitination and downregulation of Eps8." (PMID 28874189, 2017). "In lung cancer, ITSN-1s deficiency impairs Eps8 ubiquitination and favors Eps8-mSos1 interaction which activates Rac1 leading to enhanced lung cancer cell proliferation, migration and metastasis." (PMID 28874189, 2017). "Five CEU LCLs and the A549 lung cancer cell line were utilized for studies involving EPS8 knockdown." (PMID 24367505, 2013). "Our results agree with these findings, showing that EPS8 downregulation sensitizes A549 lung cancer cells to cisplatin treatment." (PMID 24367505, 2013). "In lung cancer, ITSN-1s deficiency shifts the balance in favor of greater Eps8-Sos1 interaction and less Eps8-Cbl interaction leading to activation of Rac1 and increased expression of Eps8 respectively." (PMID 28874189, 2017).
acute myeloid leukemia (3 papers, 2015 to 2019). Acute myeloid leukemia (AML) is a group of neoplasms arising from precursor cells committed to the myeloid cell-line differentiation. "Most recently, EPS8 was shown to be required for the survival of acute myeloid leukemia (AML) cells both in vitro and in vivo." (PMID 30941306, 2019). "Here, we describe the role of EPS8 in acute myeloid leukemia (AML) and consider the potential of EPS8 as an anti-AML target." (PMID 29357910, 2018).
cervical cancer (3 papers, 2013 to 2021). A primary or metastatic malignant neoplasm involving the cervix. "Interestingly, EPS8 has been specifically linked to cisplatin- and paclitaxel-induced drug response, where cervical cancer cells became more sensitive to drug treatment following EPS8 knockdown." (PMID 24367505, 2013). "Inhibition of CRM1/Exportin 1-dependent nuclear export by treatment with LMB led to the nuclear import of EPS8 in cervical cancer cells." (PMID 30941306, 2019).
hearing loss (3 papers, 2022 to 2025). "Pathogenic variants in the EPS8 gene result in nonsyndromic hearing loss." (PMID 36635257, 2023). "This potential may be similarly applied to treating different progressive forms of hearing loss, where timely intervention is crucial to prevent irreversible damage, such as TMPRSS3-related hearing loss or the EPS8 model, where EPS8 expression could not be rescued after P2." (PMID 40859056, 2025).
oral squamous cell carcinoma (3 papers, 2017 to 2022). "Our previous work in oral squamous cell carcinoma showed that Eps8 regulates integrin‐mediated invasion 29, and we therefore examined more broadly the role of Eps8 in regulating αvβ6‐dependent functions." (PMID 28608476, 2017).
pituitary tumor (3 papers, 2019 to 2022). A benign or malignant neoplasm affecting the pituitary gland. "Silence of Eps8 also inhibits cell proliferation, which suggests that Eps8 promotes pituitary tumor cell proliferation through enhancing the Raf/MEK/ERK signaling." (PMID 31231308, 2019).
gastric cancer (2 papers, 2022 to 2025). A primary or metastatic malignant neoplasm involving the stomach. "MiR-345 directly targets epidermal growth factor receptor pathway substrate 8 (EPS8), which leads to the inactivation of Rac1 and inhibits cell migration, EMT, and the cancer stem cell phenotype, thereby suppressing gastric cancer metastasis." (PMID 41188920, 2025).
leukemia (2 papers, 2018 to 2021). A malignant (clonal) hematologic disorder, involving hematopoietic stem cells and characterized by the presence of primitive or atypical myeloid or lymphoid cells in the bone marrow and the blood. "Taken together, our findings revealed the effect of CP-EPS8-NLS in inhibiting AML cells from responding to EPS8 induced activation and suppressing leukemia cells in vitro and in vivo, which demonstrates the potential of EPS8 targeting in leukemia therapies." (PMID 29357910, 2018).
lymph node metastasis (2 papers, 2013 to 2020). "Patients having higher expression of EPS8 tend to experience parametrial invasion, lymph node metastasis and a decrease in survival rate." (PMID 24367505, 2013).
Obesity (2 papers, 2010 to 2016). Accumulation of substantial excess body fat. "In this regard, our data are in agreement with the observation that mice carrying a genetic deletion of Eps8, a regulator of actin dynamics, leads to reduced body weights and partial resistance to diet-induced obesity." (PMID 27655719, 2016). "Here we show that knockout mice for Eps8, a regulator of actin dynamics, display reduced body weight, partial resistance to age- or diet-induced obesity, and overall improved metabolic status." (PMID 20209148, 2010).
squamous carcinoma (2 papers, 2014 to 2020). "Eps8 is an actin regulatory scaffold protein whose expression is increased in squamous cell carcinoma (SCC) cells." (PMID 25359883, 2014).
acute lymphoblastic leukemia (1 paper, 2018). Leukemia with an acute onset, characterized by the presence of lymphoblasts in the bone marrow and the peripheral blood. "Elevated EPS8 expression was correlated with worse outcome in infant acute lymphoblastic leukemia (ALL) based on gene expression profiles (From a Children’s Oncology Group study)." (PMID 29357910, 2018).